MIR2052 (microRNA 2052)
Synonyms: hsa-mir-2052
Gene: MicroRNA gene on chromosome 8 (74,705,693 to 74,705,747, forward strand). Ensembl gene ENSG00000283188.
Homologues: Orthologues: macaque MIR2052 (100% identical), rabbit MIR2052 (100% identical).